NOTCH1 (notch receptor 1)
Diseases named in the same sentence as NOTCH1 in open-access papers (continued):
Sharing a sentence is not in itself a finding about the gene and the disease.
glioblastoma (continued). "Specifically, we identified the ATF6 pathway of the ER stress response as a radiation responsive signaling pathway, and NOTCH1 as a previously unidentified target of ATF6 with a potential role in mediating survival of glioblastoma cells during the radiation response." (PMID 26716508, 2016). "This novel Notch1-Sp1-DR5 signaling pathway could be exploited in future therapeutic approaches for glioblastoma." (PMID 26469969, 2015). "Additionally, KLF9 directly suppresses Notch1 expression and its downstream signaling which promotes differentiation and inhibits glioblastoma neurosphere growth." (PMID 24349493, 2013). "Finally, as we previously found that NOTCH1 activation drastically reduced the rate of proliferation of glioblastoma stem cells, we also assessed the effect of NICD on the proliferation of LGG275 cells by measuring the expression of the proliferation marker MKI67 by IF and QPCR." (PMID 33925547, 2021). "Moreover, the PKCι(λ)-NOTCH1 pathway contributes to the survival of glioblastoma CSCs." (PMID 32658903, 2020). "Previously, it has been demonstrated that hypoxia could drive glioblastoma multiforme cells into a more aggressive and malignant state through Notch1-induced TRPC6 overexpression which in turn activated the calcineurin-nuclear factor of activated T-cell (NFAT) pathway and increased Ca2+ influx." (PMID 28400714, 2017). "Broad specific Notch1 inhibitors suppress glioblastoma multiforme (GBM) growth but have significant gastrointestinal toxicities." (PMID 29152141, 2017). "The co-inhibition of Notch1 and JAK1/STAT3 has also been shown to disrupt the proliferation, migration, and invasion of glioblastoma cells and to inhibit the epithelial–mesenchymal transition." (PMID 40019515, 2025). "Our findings revealed elevated levels of Notch1, CD133, and Nestin expression in glioblastomas from the GFAP-Cre; KrasG12D; APCL/+; p53L/L mice when compared to brain sections from the GFAP-Cre;KrasG12D;p53L/L group." (PMID 38473403, 2024). "In human glioblastoma explanted cultures mutant for TRIM3, transport of active NOTCH1 (NICD) is perturbed, resulting in enhanced tumor growth." (PMID 37549261, 2023). "The present study revealed that hypoxia-inducible factor-1α (HIF-1α), induced even in non-hypoxic conditions by cell-to-cell contact, was a critical cue responsible for the malignant characteristics of glioblastoma multiforme (GBM) cells through Notch1 signaling." (PMID 36183290, 2022). "Compared to the TM- and network proficient S24 glioblastoma cells, BT088 oligodendroglioma cells show a higher NOTCH1 expression, in line with the suggested role of NOTCH1 for TM network biology." (PMID 33579922, 2021). "Hypoxia increases Notch 1 activation, which in turn induces the expression of TRPC6 in primary samples and cell lines derived from glioblastoma." (PMID 34458247, 2021). "In contrast, recent studies have shown that miR-139-5p has been defined as a tumor suppressor that inhibits NOTCH1 and restrains metastasis and EMT of glioblastoma." (PMID 33430387, 2021). "The oncogenic role of Notch1 can also be due to the infection of human cytomegalovirus, which upregulates Notch1, ATF5 (an anti-apoptotic protein already highly expressed in Glioblastoma), and stem cell markers CD133, nestin, SOX2, OCT4, KLF4, and BMI-1." (PMID 30832246, 2019). "On the contrary, several groups reported a weak expression of Notch1, Notch2, MAML1, and p300 in Glioblastoma." (PMID 30832246, 2019). "We also identified Notch1 as a novel transcriptional target of ATF6, with a potential role in promoting an anti-apoptotic phenotype in irradiated glioblastoma." (PMID 26716508, 2016).
glioblastoma (continued). "For example, aggressive and malignant state of glioblastoma multiforme (GBM), the most frequent and incurable type of the brain tumor of adults, was shown to be related to an increased activation of the Notch1 provoked by hypoxia." (PMID 25866806, 2015). "Upregulating the expression levels of Notch1 and SHH likely contributed to the effect exerted by β-elemene on glioblastoma cell differentiation." (PMID 26563263, 2015). "Although DR4 has been shown to have a minor role in glioblastomas by several studies, we wanted to exclude any contribution of DR4 to the observed TRAIL sensitization upon Notch1 inhibition." (PMID 26469969, 2015). "Taken together, our results identify Notch1 as key driver for TRAIL resistance and suggest Notch1 as a promising target for anti-glioblastoma therapy." (PMID 26469969, 2015). "Differentiation of CD133+ glioblastoma stem cells into TDEC was unaffected by anti-VEGF mAb, but blocked by γ-secretase inhibition or Notch-1 silencing." (PMID 25362644, 2014). "A recent study provided some evidence that miR-146a overexpression in glioblastomas exerts an anti-tumor effect, seemingly related to the capacity of this microRNA to target in these cells the 3' UTR of the NOTCH1 mRNA." (PMID 22453030, 2012). "Notch1 is deemed to be activated in primary glioblastoma, whereas low-grade astrocytomas seem to show an inactive Notch signaling." (PMID 33190170, 2021). "Notably, positive staining of glioblastoma for HEY1 and Notch1 correlated with worse prognosis of patients and resistance to chemo- and radiotherapy." (PMID 34680255, 2021). "Thus, our data imply that at least two, partially additive and complementary, niches of cellular resilience exist in glioblastoma: a PVN and a TM connectivity niche, that inversely depend on NOTCH1 expression." (PMID 33579922, 2021). "In this study, we correlated glioblastoma locations with the expression of five mesenchymal genes (VEGFC and its receptor FLT4, HGF and its receptor MET, and CHI3L1) and five proneural genes (PROM1, NOTCH1, DLL3, PDGFRA, and BCAN)." (PMID 26637806, 2016). "In particular, in contrast with PV-FP and PV-O subtype, PV-T glioblastomas were characterized by a high expression of the mesenchymal marker VEGFC and the proneural and CSC markers NOTCH1 and PROM1 that could be potential targets for specific therapies." (PMID 26637806, 2016). "Li found that downregulation of NOTCH1 expression could suppress the proliferation and induce the apoptosis of U373MG and SHG44 glioblastoma cells." (PMID 25149541, 2014). "In glioblastoma-derived neurospheres enriched with cancer stem cells, KLF9 was found to induce cell differentiation, suppress neurosphere formation, and inhibit xenograft growth by binding to the Notch1 promoter to repress Notch1 expression and downstream signaling." (PMID 40860800, 2025). "TRPM7 expression in glioblastoma cells was found to be positively correlated with Notch1 signaling activity and CD133 and ALDH1 expression; briefly, downregulation of TRPM7 by siTRPM7 decreased Notch1 signaling whereas upregulation of TRPM7 increased Notch1 signaling." (PMID 34458247, 2021). "Concerning glioblastoma (GBM), it has been reported that transient transfection of miR-34a mimics into glioma and medulloblastoma cell lines remarkably inhibits cell proliferation, invasion, survival, and cell cycle progression by targeting c-Met, Notch-1, and Notch-2." (PMID 32083078, 2020). "Then, we examined NOTCH1, CDH2 and SNAI1 three-gene signature in the Glioblastoma Multiforme (GBM) cohort (TCGA, Provisional, n = 577) and demonstrated its association with decreases in DFS (P < 0.05)." (PMID 30170559, 2018).
prostate carcinoma (96 papers, 2010 to 2025). A carcinoma that arises from epithelial cells of the prostate gland. "In this study, high Notch1 expression was significantly associated with high-grade tumors, a finding also noted in prostate cancer and hepatocellular carcinoma." (PMID 40060224, 2025). "When TAMs interact directly with prostate cancer cells, downstream factors associated with NOTCH1 signaling are significantly upregulated." (PMID 39286635, 2024). "Previous studies have shown that SIRT1, Notch1, c-Myc, and downstream targets of miR-34a are positively associated with prostate cancer stem cell traits." (PMID 37960146, 2023). "Loss of NOTCH1 is able to reduce the oncogenic potential of prostate cancer cells, by compromising their ability to form tumor spheres and metastasize." (PMID 35954292, 2022). "Increased Notch 1 activity has been shown in a PTEN loss-of-function preclinical model of prostate cancer and treatment with GSIs can effectively elicit tumour growth arrest." (PMID 32575680, 2020). "MiR-34b-3p regulates the expression of stem cell-related factors, including c-Myc, Sox2, Met and Notch1, which have also been implicated in prostate cancer." (PMID 26107383, 2015). "In prostate cancer for instance, upregulated levels of Notch 1 are highly associated with prostate cancer development, metastasis, and progression." (PMID 25717438, 2014). "Meanwhile, NOTCH1, classified as a “Variant of Uncertain Significance”, may be involved in cell fate determination, potentially suppressing tumorigenesis by impeding prostate cancer invasion." (PMID 40124187, 2025). "Notch1 associated with epithelial-mesenchymal transition (EMT) in prostate cancer." (PMID 30001383, 2018). "Notably, the overexpression of Notch1, Notch3 and PlexinD1 induces Slug transcription factor and downregulates E-cadherin levels in prostate cancer cells, a phenotype associated with increased cell migration and metastatic potential in vivo." (PMID 27749937, 2016). "Moreover, knockdown of Notch1 inhibited invasion of human prostate cancer cells in association with inhibition of matrix metalloproteinase-9 (MMP-9) and urokinase plasminogen activator." (PMID 22970326, 2012). "Finally, to investigate whether over-activation of Notch1 signaling causes prostate cancer, we observed the prostates of 1.5-year-old male mice." (PMID 38538986, 2024). "Overexpression of Notch-1 in prostate cancer promotes prostate cancer cell migration and invasion, whereas downregulation of Notch-1 expression inhibits prostate cancer cell migration and invasion that occur through induction of EMT." (PMID 40630953, 2025). "In particular, Notch-1 was overexpressed in bone metastasis vs. primary prostate cancer tissue, suggesting that upregulation of Notch-1 plays a significant role in bone metastasis." (PMID 38131796, 2023). "CXCL6 production is up‐regulated in aged prostate stroma and promotes proliferation of both prostate stromal fibroblasts and epithelium, and increased CXCL6 expression occurs in prostate cancers with high Notch1 levels." (PMID 36608258, 2023). "Veterans with prostate cancer exhibited a mutational landscape broadly similar to prior studies, including KMT2A and NOTCH1 mutations associated with neuroendocrine prostate cancer phenotype, previously reported to be enriched in veterans." (PMID 38050021, 2023). "The increased expression of LINCO1638 lncRNA and NOTCH1 has been observed in prostate carcinoma patients." (PMID 37628760, 2023). "Correspondingly, Notch1 overexpression promoted EMT marker expression, whereas Notch1 siRNA suppressed cell migration and invasion in prostate cancer cells." (PMID 36012128, 2022). "LncRNA GHET1 reduces KLF2 expression to trigger HIF-1α/Notch1 signaling in increasing prostate cancer progression." (PMID 35773731, 2022).
prostate carcinoma (continued). "The inhibition of Notch-1 signaling restores the sensitivity of breast cancer cells and prostate cancer cells to doxorubicin and docetaxel." (PMID 35684449, 2022). "Its antitumor activity was reported to be related to its inhibition of Notch signaling through Notch-1 downregulation in prostate cancer cells (PC-3)." (PMID 36422542, 2022). "ERG-dependent NOTCH1/2 upregulation promotes EMT in prostate cancer cells, which can be reversed upon ERG and NOTCH1/2 silencing." (PMID 35954292, 2022). "Notch signaling has been reported to become activated in prostate cancer cell lines exhibiting resistance to the clinically available AR inhibitor enzalutamide, as verified by the increased levels of cleaved NOTCH1, HES1 and c-MYC." (PMID 35954292, 2022). "It has been found that grape seed extract proanthocyanidins significantly reduce constitutive and Jagged1 (Notch1 ligand)-induced activation of the Notch1 pathway to target prostate cancer growth and tumor recurrence." (PMID 34206588, 2021). "Knock-down of NOTCH1 results in a concomitant decrease of MMP9 expression in prostate cancer cells, and of MMP2 and MMP9 in BrCa cells." (PMID 33430387, 2021). "Curcumin inhibited Notch1 activity, arrested the cell cycle in G0/G1 stages, and led to caspase-dependent apoptosis in prostate cancer cells." (PMID 34680255, 2021). "In castrate-resistant prostate cancer cells, DIM induced the expression of miR-34a which was accompanied by decreased self-renewal of prostate cancer cells and suppression of Notch-1 and androgen receptor signaling." (PMID 35582221, 2020). "Silencing the Notch1 gene by SiRNA promoted docetaxel-induced cell growth inhibition, apoptosis, and cell cycle arrest in prostate cancer cells." (PMID 32630477, 2020). "A recent study has indicated that Notch 2 is overexpressed in enzalutamide-resistant prostate cancer patients, while cleaved or activated Notch 1 and HES-1 levels were increased in enzalutamide-resistant cell line models." (PMID 32575680, 2020). "In prostate cancer, Notch1 silence inhibits invasion through matrix metalloproteinase-9 (MMP9) and urokinase plasminogen activator (uPA)." (PMID 31477177, 2019). "Notch1 is the best-studied member of the family, and it is often overexpressed in human breast, colorectal, lung, pancreas, and prostate cancers." (PMID 29462871, 2018). "Notch1 has tumour-suppressing and promoting functions in human prostate cancer or in different tumours." (PMID 30170559, 2018). "ALDH1A1 is known to be regulated by NOTCH signaling and NOTCH1 plays a prominent role in prostate cancer cell proliferation and migration." (PMID 29259971, 2017). "In this report, we have unraveled a novel link between Pim kinases and Notch1, which is relevant for the progression of both breast and prostate cancer." (PMID 27281612, 2016). "To further verify the cross-talk between Pim and Notch proteins in prostate cancer, we analysed the presence of nuclear Notch1 in orthotopic prostate xenografts." (PMID 27281612, 2016). "Interrogating public data repositories (i.e. Oncomine, GEO, ArrayExpress and the cBioportal), we found conflicting information on levels of Notch1 mRNA in prostate cancer." (PMID 27384993, 2016). "Notch1 signaling appeared to be particularly relevant in regulating PlexinD1 mRNA levels in prostate cancer cells PC3 and DU145, and this was confirmed at the protein level." (PMID 27749937, 2016). "Consistently, in Tomlins we found decreased expression of the Notch1 gene already in precursor lesions of prostate cancer (HGPIN)." (PMID 27384993, 2016). "PlexinD1 showed a positive Spearman correlation coefficient with Notch1 levels, ranging from 0.43 (prostate cancer) to 0.75 (kidney renal clear cell carcinoma)." (PMID 27749937, 2016).
prostate carcinoma (continued). "Phosphorylation of Notch1 by Pim kinases promotes motility of prostate cancer cells, as demonstrated both by the phosphomutants and by the ability of either Pim or Notch inhibitors to block the pro-migratory effects of Notch or Pim proteins, respectively." (PMID 27281612, 2016). "Out of the majority of prostate cancer cells that are growth arrested by activated Notch1 expression, we were able to select a few colonies that kept proliferating." (PMID 27384993, 2016). "As previously said, several published prostate cancer datasets contain samples with upregulated Notch1 expression compared to normal prostate tissue." (PMID 27384993, 2016). "A comparable study in prostate cancer demonstrated that knocking down Notch1 sensitized the cells to treatment with docetaxel." (PMID 28036048, 2016). "To better investigate the growth suppressing effects of Notch1 in prostate cancer cells expressing low levels of this gene, we looked for well-established tumor suppressors among the genes induced by Notch1 in PC3 cells." (PMID 27384993, 2016). "Conversely, among the genes inhibited by Notch1 in cells and down-regulated in Notch_high PCas there were targets with tumor suppressing function in prostate cancer." (PMID 27384993, 2016). "More specifically, we found that Notch1 overexpression in prostate cancer cell lines both induces and inhibits gene networks associated with cell cycle and proliferation in prostatic neoplasms." (PMID 27384993, 2016). "Taken together, these data indicate that Notch growth suppressing effects in prostate cancer cells with low Notch1 levels are mediated by p21WAF1/CIP1 in a Smad3 dependent manner." (PMID 27384993, 2016). "A recent review by Carvalho and coworkers reveals that increased Notch1 can confer a survival advantage on prostate cancer cells, but also that Notch1 signaling can antagonize growth and survival of both benign and malignant prostate cells." (PMID 27384993, 2016). "Taken together, miR-34 family directs the regulation of Notch 1 and 2 protein expression in glioma cells, pancreatic, and prostate cancer cells mediating the suppression of self-renewal and differentiation properties of CSCs." (PMID 25717438, 2014). "Re-expression of miR-34a in C4-2B and CWR22rv1 prostate cancer cells reduced the expression of Notch1, decreased the self-renewal capacity and inhibited the growth of prostate cancer cells." (PMID 25717438, 2014). "Notch1 has been shown to inhibit the cell growth of hepatic carcinoma, small cell lung cancer and prostate cancer in a previous study." (PMID 23599800, 2013). "Down-regulation of Notch1 and its ligand Jagged-1 has been shown to inhibit proliferation of prostate cancer cells." (PMID 22970326, 2012). "Based on these results, we conclude that Notch1 activation is largely dispensable for SFN-mediated inhibition of prostate cancer cell migration." (PMID 22970326, 2012). "Collectively, these results indicated that SFN treatment resulted in cleavage of Notch1, Notch2, and Notch4 in both androgen-independent and androgen-responsive human prostate cancer cells." (PMID 22970326, 2012). "On the other hand, targeted depletion of Notch2 by siRNA as well as inhibition of Notch1 activation using DAPT augments prostate cancer cell motility inhibition by PEITC." (PMID 22039516, 2011). "The same group of investigators reported later that RNA interference of Notch1 conferred protection against prostate cancer cell migration and invasion." (PMID 22039516, 2011). "In human prostatic cancer cells, knock-down of Notch1 resulted in a downregulation of MMP9 and uPA and its receptor, uPAR." (PMID 21349159, 2011). "Additionally, in prostate cancer it has been shown that NOTCH1 silencing decreased BCL-2 levels which increased sensitivity to chemotherapy, suggesting a similar mechanism for the interplay of AZ1 and venetoclax." (PMID 40456839, 2025).